HYAL1 (hyaluronidase 1)
Diseases named in the same sentence as HYAL1 in open-access papers (continued):
Sharing a sentence is not in itself a finding about the gene and the disease.
tumor (75 papers, 2006 to 2025). "Specifically, ECM-associated genes such as SERPINH1, SPARCL1, and HYAL1 have been implicated in modulating immune cell behavior within the tumor milieu." (PMID 40426943, 2025). "A study utilizing tumor spheroids to model cancer stem cells demonstrated that elevated HYAL1 expression is associated with increased metastatic potential in vivo." (PMID 41421148, 2025). "Most notably, we identify elevated levels of Hyal1 and Hyal2 in tumor-association macrophages (TAMs), suggesting a role for TAM-mediated turnover of HA in the TME." (PMID 36723776, 2023). "Multiple data indicate that HYAL-1 expression is associated with tumor progression and poor clinical outcomes." (PMID 36613567, 2022). "It is known that hyaluronidase (encoded by HYAL-1) dissolves hyaluronic acid into small fragments which promotes angiogenesis, possibly leading to increased tumor growth and metastasis." (PMID 34679042, 2021). "The HYAL1 gene resides in chromosome 3p21.3 and is associated with tumor suppression suggesting its possible role in regulating cell proliferation." (PMID 32258117, 2020). "BCa is the first cancer model system in which HYAL-1 was found to be a molecular determinant of tumor growth, invasion, and angiogenesis and also as a diagnostic and prognostic marker." (PMID 27419371, 2017). "In such context, it would be interesting to address the potential of HYAL1 upregulation to associate with metastatic phenotype and/or tumor resistance resulting in poor prognosis." (PMID 27764788, 2016). "Chromosomal aberrations and instability at the 3p21.3 locus and homozygous deletions targeting HYAL1/2/3 have been frequently found in many epithelial cancers, suggesting a potential role of tumor suppressor for the genes encoded at this locus." (PMID 27764788, 2016). "Hyal1 and Hyal2 are most often associated with damaged or tumor-associated stroma undergoing remodeling." (PMID 26106384, 2015). "Instead, tumor cells show markedly reduced hyaluronanlevels, which is associated with increased Hyal-1 expression." (PMID 26352698, 2015). "Expressions of HAS1, HAS2 (HA synthases) and HYAL1 (hyaluronidase), have been shown to be associated with diagnosis and prognosis of various tumor types." (PMID 24244714, 2013). "In contrast, levels of both hyaluronan and HYAL-1 have been reported to be increased in bladder, prostate and head and neck cancers, and to be implicated in tumor progression and metastasis." (PMID 21695196, 2011). "In accordance with this concept it has been reported the high expression of HA in tumor associated stroma and increased HYAL-1 (Hyaluronidase) enzyme synthesis on tumor epithelial cells in high-grade prostate carcinoma." (PMID 16401353, 2006). "HYAL1 is positively correlated with effector memory CD8+ T cells and Type 17 helper (Th17) cells—both associated with anti-tumor immune responses—suggesting that HYAL1 may contribute to the activation or maintenance of tumor-reactive immunity." (PMID 40426943, 2025). "In addition, the reduced HYAL1 expression is associated with the depletion of E-cadherin, hinting at invading tumor cells undergoing EMT." (PMID 33809973, 2021). "HYAL1 and tumor-associated HA/HAase system can promote tumor growth, invasion and metastasis." (PMID 32596162, 2020). "This could mean that the loss of HYAL1 as well as an increase in HA could be a great candidate for tumor markers." (PMID 32610620, 2020). "Since the tumor-associated HA-HAase system is active in a variety of carcinomas, the broader implication of this study would be that targeting of HYAL-1 with small molecule uncompetitive inhibitors could be a potential avenue for cancer therapy." (PMID 27419371, 2017). "Furthermore, patients with a history of BCa who have elevated HYAL-1 mRNA or urinary HAase levels are at an increased risk for BCa recurrence (i.e. emergence of a new tumor in the bladder) within six months." (PMID 27419371, 2017).
tumor (continued). "In tumor tissues, HYAL-1 degrades tumor-associated HA into fragments, some of which are angiogenic." (PMID 27419371, 2017). "Tumor cells express HAS1–3 throughout the disease course, whereas expression of HYAL1 and 2 decrease in the tumor stage, leading to HA accumulation." (PMID 39858106, 2025). "Future research must decipher HYAL1′s context-specific roles within tumor heterogeneity, elucidate its epigenetic regulation, and develop targeted strategies." (PMID 41421148, 2025). "Tumor cells containing Hyal1 produced more EVs and grew more quickly into three-dimensional spheroids from which cells emerged more rapidly on collagen." (PMID 39851567, 2025). "HYAL1 exhibits a perplexing dual role in cancer: it demonstrates pro-tumor properties in some aggressive cancers yet displays anti-tumor effects in specific therapeutic contexts." (PMID 41421148, 2025). "A tendency toward decreased HYAL1 expression was noted in the tumor stage compared with the patch stage." (PMID 39858106, 2025). "The treatment of prostate stromal cells with tumor-derived EVs containing Hyal1 specifically promoted stromal cell motility via FAK and β1 integrin on the stromal cells." (PMID 39851567, 2025). "From a functional perspective, catalytically active HYAL1 enhances the endocytic efficiency of tumor cells, enabling more effective acquisition of external resources." (PMID 41421148, 2025). "•Mechanistic Complexity: HYAL1 influences tumor progression through multiple pathways, including HA degradation, endocytosis enhancement, MMP/TIMP balance regulation, integrin activation, and cytoskeletal reorganization." (PMID 41421148, 2025). "2.Accounting for Tumor Heterogeneity: HA metabolism undergoes dynamic changes during tumor progression, and HYAL1 function is likely to vary significantly across cancer stages and molecular subtypes." (PMID 41421148, 2025). "This functional contradiction underscores the context-dependent nature of HYAL1, whose activity and effects are profoundly influenced by tumor type, microenvironmental features, and epigenetic regulation." (PMID 41421148, 2025). "The enzymatic degrading of hyaluronic acid by tumor cell-specific enzymes (e.g., hyaluronidase-1) significantly accelerates docetaxel release from nanogels." (PMID 38247784, 2024). "As a result, the nanogels selectively inhibited MCF-7 tumor cell growth in vitro (via the CD44 receptor and the hyaluronidase-1 enzyme), indicating their therapeutic potential for efficient tumor ablation." (PMID 38247784, 2024). "As a result, the nanogels internalized into the MCF-7 cells via CD44 receptor-mediated endocytosis allowed for stimulated DTX release via Hyal-1 enzymes abundant in tumor cells." (PMID 38247784, 2024). "While the regulation of GAGs is very complex and finely regulated, especially in cancer, some literature suggests that HYAL1 is essential for metastasis and tumour growth." (PMID 38689429, 2024). "While HYAL1 overexpression can induce migration, invasion, and metastasis in different cancer models, HYAL1 can also function as a tumor suppressor in some cancers." (PMID 37296612, 2023). "Variable levels of HYAL1 expression were seen in all tumor specimens, with the highest HYAL1 expression observed in PDAC specimen #3." (PMID 37296612, 2023). "Most notably, we identify elevated levels of the hyaluronidases Hyal1 and Hyal2 in tumor-association macrophages (TAMs), suggesting a role for TAM-mediated turnover of HA in the tumor microenvironment (TME)." (PMID 36723776, 2023). "Strikingly, F4/80 + macrophages derived from both tumor models expressed elevated levels of Hyal1 and Hyal2, suggesting that TAMs play a pivotal role in HA degradation." (PMID 36723776, 2023). "The impact of Hyal-1 expression on tumor cell interaction with the brain endothelium should be confirmed by overexpressing HA-metabolizing enzymes." (PMID 36291142, 2022). "Next, the impact of HYAL1 KO on tumor cell interaction with the brain endothelium was studied in vitro." (PMID 36291142, 2022).
tumor (continued). "We have previously demonstrated that high tumoral Hyal-1 expression levels in the primary tumor significantly correlate with BM development in BC patients." (PMID 36291142, 2022). "CS, a natural biodegradable polysaccharide, can recognize the glycoprotein CD44 receptors overexpressed on tumor cells and can be decomposed by hyaluronidase-1 (Hyal-1)." (PMID 36195918, 2022). "In line with the previous data, we observed a significant reduction in tumor cell invasion in both HYAL1 KO clones compared to the control cells, with clone KO #1 showing a more pronounced effect." (PMID 36291142, 2022). "In the tumour tissue, 3 of 12 and 11 samples, respectively, showed low to medium HYAL1 and HYAL2 expression, being undetectable in the remaining samples." (PMID 35767191, 2022). "Another advantage of HA is that it can be degraded by hyaluronidase 1(Hyal-1), which is highly expressed in a variety of malignant tumor cells, destroying the spatial structure of HA-NPs to release the encapsulated drugs." (PMID 36145668, 2022). "Decreased HYAL1 expression also correlates with early disease recurrence in endometrial carcinoma, larger tumor sizes and lymphovascular invasion." (PMID 33809973, 2021). "It is well known that members of the family of molecules of the HA signaling pathway, like HA synthases (HAS1, HAS2, HAS3), HA receptors and hyaluronidases (mainly HYAL1) are critical determinants of tumor growth and progression." (PMID 32610620, 2020). "The overall function is believed to be tumor type or concentration dependent as with prostate cancer; cell proliferation was suppressed at a high HYAL1 concentration and vice versa." (PMID 32258117, 2020). "On the other hand, several members of the HA signaling pathway, like HA synthases (HAS1, HAS2, HAS3), HA receptors and hyaluronidases (mainly HYAL1) are critical determinants of growth and progression of the tumor." (PMID 32610620, 2020). "HA, together with its receptor (CD44) and degradation enzymes (HYAL-1, etc.), acts as a carcinolytic agent, suppressing tumour growth and metastasis and this is evidenced by accumulation of HA and its associated degradation enzymes within malignant tumours." (PMID 30966217, 2018). "We have previously shown that HYAL-1 is the tumor-derived HAase expressed in BCa cells and it is secreted in the conditioned media." (PMID 27419371, 2017). "Tumor cell-derived hyaluronidase HYAL-1 degrades hyaluronic acid (HA) into angiogenic fragments (AGF: 10-12 disaccharides)." (PMID 27419371, 2017). "We have previously shown that silencing of HYAL-1 expression in the HT1376 xenograft model leads to the inhibition of tumor growth, invasion and angiogenesis." (PMID 27419371, 2017). "Based on the phenotypic readouts, mechanistic studies and activity of sHA-F in two xenograft models, our study demonstrates that tumor-derived HAase, HYAL-1 can be targeted to control BCa growth and progression." (PMID 27419371, 2017). "Although aberrant HYAL1 expression often correlates with increased tumor malignancy involving unstable 3p21.3 locus activity, the mechanism regulating HYAL1 expression and other genes at this locus in cancer cells remains poorly understood." (PMID 27764788, 2016). "For example, it has been shown that HYAL-1 acts as a tumor promoter at a naturally expressed level by tumor cells, while above the naturally expressed level (exceeding 100 mU/106 cells) it acts as tumor suppressor through inducing apoptosis." (PMID 27200096, 2016). "Further, we also analyzed these peak fractions for potential to inhibit HYAL1, a tumor specific hyaluronidase that was inhibited by BIRM." (PMID 27705939, 2016). "In view of the reported tumor-promoting actions of Hyal1, it is also important to note that preclinical models have consistently shown a reduction in metastatic spread with PEGPH20 treatment." (PMID 26380222, 2015).
tumor (continued). "A study of patients with endometrial cancer indicated that tumor tissues had elevated HA levels and correlated with lower expression of Hyal-1 and Hyal-2 compared to healthy controls." (PMID 26029216, 2015). "Previous studies revealed that increased HAS1 isoenzyme and Hyal1 expression in human BC were predictive for muscle-invasive tumor growth, metastasis and poor disease-specific survival." (PMID 24069434, 2013). "Conversely, in patients with ovarian cancer, Nykopp and colleagues reported that downregulation of HYAL1, with the concomitant decrease in hyaluronidase activity, is correlated with elevated tumor HA content." (PMID 24213471, 2012). "In bladder and prostate cancer cells, HYAL1 seems to be the major tumor-derived hyaluronidase and inhibition of hyaluronidase activity has been shown to suppress LNCaP-AI prostate tumor growth in a xenograft mouse model." (PMID 24213471, 2012). "It is possible that elevated HYAL-1 levels would also have a tumor promoter role in clear cell and mucinous EOCs, and future functional studies are warranted to test this interesting possibility." (PMID 21695196, 2011). "Among the six mammalian Hyals, Hyal-1 is the major tumor-derived Hyal and is expressed by a variety of tumor cells, confirmed with several methods (RT-PCR analysis, cDNA cloning, protein purification, immunoblotting and immunohistochemistry)." (PMID 20849597, 2010). "Recent findings have suggested that depending on its concentration, HYAL1 can function either as a tumor promoter or as a suppressor." (PMID 20875124, 2010). "It has been reported that hyaluronidases act as tumor inhibitors in vivo, Hyal-1 reversibly correlates with hyaluronan content and that Hyal-1 correlates with tumor grade, stage, and multifocality." (PMID 20849597, 2010). "Recent findings have suggested that depending on its concentration, HYAL1 can function as a tumor promoter or as a suppressor." (PMID 19435493, 2009). "In contrast, experimental overexpression of HYAL1 in a rat colon carcinoma cell line inhibits tumor growth and generates necrotic tumors." (PMID 19435493, 2009). "In an invasive bladder cancer cell line, blocking of HYAL1 expression decreases tumor growth, inhibits tumor infiltration and decreases microvessel density." (PMID 19435493, 2009). "Many tumor suppressorcandidate genes such as CACNA2D2, DLC1, FUS1, H37, HYAL1, RASSF1A, SEMA3B, andSEMA3F and tumor susceptibility genes such as hMLH1 have been isolated from theregion." (PMID 18288251, 2007). "Functionally, HYAL1 knockdown not only suppressed PDAC cell proliferation but also significantly induced caspase-3 and PARP cleavage, suggesting that HYAL1 deficiency promotes tumor cell apoptosis." (PMID 41421148, 2025). "However, translating this potential into clinical value necessitates a clear understanding of the context-dependent mechanisms of HYAL1 across different tumor types and microenvironments." (PMID 41421148, 2025). "Given that PDAC features prominent stromal hyperplasia and hypoxia, the actual function of HYAL1 during tumor progression might be compromised or masked by compensatory mechanisms involving other hyaluronidases such as KIAA1199." (PMID 41421148, 2025). "Of particular interest is the potential tumor-suppressive role of HYAL1." (PMID 41421148, 2025). "We found that the levels of combination signatures CM-2 (HYAL-1 + N-Cadh) and CM-6 (HYAL-1 + N-Cadh + HAS-2 + SNAI1 + Slug + MMP-9) were elevated 5–8-fold in tumor specimens from patients who had or developed metastasis during follow-up compared to those who did not (p < 0.0001)." (PMID 40149256, 2025). "This interaction may represent a key molecular mechanism through which HYAL1 modulates the tumor microenvironment." (PMID 41421148, 2025).
tumor (continued). "In tumoral areas, the biopolymer coating can be efficiently removed by the hydrolysis catalyzed in the first extent by hyaluronidase-2 (Hyal-2), present on cancer cells membranes, and then by hyaluronidase-1 (Hyal-1) after mediated endocytosis." (PMID 36839771, 2023). "Once inside the tumor microenvironment, drug release is then triggered by Hyal-1." (PMID 36839771, 2023). "End products generated from HA degradation may potentiate tumor progression, which has been suggested by studies showing increased tumor cell growth and migration following overexpression of the mammalian hyaluronidase HYAL1." (PMID 36230537, 2022). "HYAL-1 acts as a tumor enhancer at naturally occurring levels." (PMID 36613567, 2022). "We could previously show a significant association between the expression of the synthase HAS2 and the hyaluronidase HYAL1 in the primary tumor of BC patients and the development of BM." (PMID 36291142, 2022). "Here, a reduced CD44 expression led to significantly less adhesion (32% less adhesion) to brain endothelial cells compared to the control cells, with a relative number of adherent tumor cells (shCD44) to the brain endothelium similar to those of the HYAL1 KO cells." (PMID 36291142, 2022). "It is possible that an altered balance between HAS2 and HYAL1 upon UGT2B28 KD may contribute to the delay in tumor take and tumor growth, which would need to be verified in the future using additional experiments." (PMID 35954173, 2022). "In addition, N-glycosylation in Hyaluronidase 1 (HYAL-1) is required for its secretion and thus regulates enzymatic activity, while upregulation of HYAL-1 is reported to be linked to tumour cell proliferation and angiogenesis in multiple cancers." (PMID 36611811, 2022). "Studies in animals indicate that HYAL2 or HYAL1 inhibits tumor growth and may control intercellular interactions." (PMID 34540372, 2021). "The function of HYAL1 was proposed to be as tumor suppressor as well as promoter." (PMID 32610620, 2020). "However, our results show that although we saw a decrease in HYAL1 in tumor tissue, we also saw a decrease in HA levels." (PMID 32610620, 2020). "Similarly, exposure of tumor cells to hyaluronidases alone (e.g., HYAL1 or PH-20) can be growth-suppressing and increase response of tumor cells to therapy." (PMID 29868579, 2018). "Drug release was then triggered by Hyal-1 present in the tumour microenvironment." (PMID 29410811, 2018). "Hyaluronidases PH-20, Hyal-1 and Hyal-2 induce the expression of tumor suppressor WWOX." (PMID 27845895, 2017). "Since HYAL-1 promotes tumor invasion and metastasis, we investigated whether sHA-F inhibits chemotactic motility and invasiveness of BCa cells and whether AGF addition prevents both activities." (PMID 27419371, 2017). "Hyal-1 is a lysosomal enzyme that is secreted from cells, and is considered as a tumor suppressor." (PMID 27845895, 2017). "sHA-F inhibited tumor growth in HYAL-1 expressing xenograft models." (PMID 27419371, 2017). "Overexpression of Hyal-1 also promoted mammary tumor growth and increased tumor angiogenesis." (PMID 26029216, 2015). "In preclinical studies, for instance, overexpression of HYAL2 has been observed to stimulate tumor growth in a mouse model of astrocytoma, and Tan and co-workers have reported that HYAL1 overexpression promotes tumor growth and angiogenesis in a breast cancer xenograft model." (PMID 24213471, 2012). "Interestingly, elevated extracellular hyaluronan is mainly found in tumor stroma while elevated HYAL-1 levels are detected in tumor tissues, suggesting a cross-talk between these two tissue types." (PMID 21695196, 2011). "Also experimental overexpression of HYAL1 in a rat colon carcinoma cell line inhibits tumor growth and generates necrotic tumors." (PMID 20875124, 2010). "In contrast to the tumour suppressor function of HYAL1 and HYAL2 in these studies, no frequent inactivating mutations were identified so far in these genes." (PMID 18725949, 2008).